MDM2 (MDM2 proto-oncogene)
Diseases named in the same sentence as MDM2 in open-access papers (continued):
Sharing a sentence is not in itself a finding about the gene and the disease.
cancer (continued). "The overexpression of MDM2 is linked to a poor prognosis for patients with cancer." (PMID 33291373, 2020). "Many studies have found MDM2 gene mutations in the intestinal system to be associated with cancer." (PMID 32224842, 2020). "Mdm2 overexpressed is a hallmark in several types of cancer." (PMID 32982771, 2020). "The rs309 locus in the second promoter region of the MDM2 gene, which is associated with increased expression of this gene, may have potential as a molecular target for cancer susceptibility and as suitable tumor marker." (PMID 32224842, 2020). "Further confounding the risk association of cancer with SNP309G is the presence of another MDM2 variant, SNP285C, which is found only in Caucasian populations (~12% of all SNP309G alleles) and strongly reduces the binding of Sp1 to the MDM2 promoter, antagonizing the effects of SNP309G." (PMID 31152665, 2019). "Failures in the pathways that control MDM2 switch-off have been linked to cancer development." (PMID 31878315, 2019). "The impact of MDM2 SNP309 on cancer predisposition and age of onset." (PMID 31152665, 2019). "While MDM2 inhibitors are currently in clinical trials as primary cancer therapeutics, the loss of senescence-associated IL-6 secretion suggests they may also be useful as adjuvants to senescence-inducing chemotherapies." (PMID 29402901, 2018). "Despite the co-amplification of genes encoding CDK4 and MDM2 in human malignancies, our results indicate that targeting both simultaneously may be counterproductive for cancer therapy." (PMID 30206211, 2018). "In this retrospective study, we assessed the occurrence of MDM2 amplification among patients with various types of cancers and its association with clinical factors, other genetic aberrations, and response to targeted therapy in a phase I clinical trial setting." (PMID 30237864, 2018).
cancer (continued). "Furthermore, the proliferation of primary cells as well as cancer cells was impaired upon simultaneous loss of Mdm2 and RING1B, suggesting synthetic lethality." (PMID 27927750, 2017). "Furthermore, amplification and overexpression of MDM2 have been implicated in various types of cancer." (PMID 28415963, 2017). "In addition, mutations on the MDM2 side of interaction emerged from an in vitro selection assay involving nutlin-3, suggesting another means of escape mutation acquisition by cancer cells." (PMID 26992014, 2016). "It remains to be determined whether the partial resistance of human cancers to MDM2 drugs in clinical trials 8 is linked to density effects on MDM2 functions." (PMID 27273042, 2016). "Recent data suggested that MDM2 gene polymorphisms may contribute to increased MDM2 basal expression and increase cancer susceptibility." (PMID 27506496, 2016). "Firstly, there is a limited number of studies that have actually analysed MDM2 SNP285 polymorphism with cancer susceptibility and the total sample size was relatively small, which may lead to relatively weak power to detect the real association." (PMID 27890964, 2016). "Multiple mdm2 splice variants are found in G/G SNP309 cancer cell lines." (PMID 26416444, 2015). "Whether high-level MDM2 expression is also associated with the regulation of MDM2 protein stability in cancer is less understood." (PMID 25888903, 2015). "Although patients with high MDM2 positivity may obtain a CR state clinically, it is still necessary to closely observe them because these patients may be at high risk for cancer recurrence." (PMID 25880782, 2015).
cancer (continued). "Further, this variant may confound cancer risk evaluations related to other SNPs in the MDM2 gene (such as SNP309) depending on the ethnic population investigated." (PMID 25327560, 2014). "Recently, new SNPs on MDM2 were discovered and shown to be associated with different cancer types." (PMID 24708820, 2014). "We hypothesized that high mdm2-C transcript levels encoded from the G allele mdm2 SNP309 in human cancers would result in high levels of endogenous MDM2-C protein and would confer oncogenic functions." (PMID 24147044, 2013). "MDM2 might influence cancer risk through its interaction with other key cancer genes with various functions." (PMID 23244604, 2012). "It is therefore of interest to search for additional variants in the MDM2 promoter that may contribute to altered cancer risk." (PMID 22558411, 2012). "However, the exact molecular mechanisms underlying Mdm2 overexpression in human cancers remain largely elusive." (PMID 22976441, 2012). "Whether MDM2 SNP309 polymorphism has a correlation with the prognosis of cancers remains controversial." (PMID 22844496, 2012). "Two polymorphisms located in the MDM2 promoter P2 have been shown to affect cancer risk." (PMID 22558411, 2012). "MDM2 has been linked to cancer development, progression, and metastasis." (PMID 22911819, 2012). "Furthermore, mutations in the Mdm2 oncoprotein that disrupt ribosomal protein (RP)-mediated suppression of Mdm2 E3 ligase activity have been observed in human cancers." (PMID 22976441, 2012). "A cancer-associated cysteine-to-phenylalanine point mutation in the zinc finger domain of Mdm2 causes disruption of L11 and L5 binding to Mdm2, and based on this in vitro data, we previously generated a knock-in mouse with the Mdm2 C305F mutation." (PMID 21747916, 2011).
cancer (continued). "How does the TT genotype lead to increased cancer risk is at present not well understood, but there is evidence to suggest that the role of MDM2 in tumorigenesis may vary in a gender-specific manner, and between smokers and never smokers." (PMID 20219101, 2010). "Alternatively, other MDM2-dependent pathways could be modified in the TT subjects, leading to cancer susceptibility." (PMID 20219101, 2010). "Mdm2 is frequently overexpressed in human cancers while the molecular mechanisms underlying the timely destruction of Mdm2 remain unclear." (PMID 21317463, 2010). "In the current study we analyzed the relationship between MDM2 309 SNP status and cancer in a large group of Ashkenazi patients including a large group of BRCA1/2 mutation carriers Our results revealed high percentage of MDM2 309 SNP in this population of around a quarter of all women." (PMID 19226467, 2009). "Recent data suggest that the promoter polymorphism in the MDM2 gene may influence the age of cancer onset in a gender specific way." (PMID 18433484, 2008). "It is intriguing to hypothesize that the SNP309 locus could contribute to the increased cancer risk observed in female carriers though the preferential estrogen-dependent stimulation of MDM2 transcription from the G-allele of SNP309." (PMID 18398474, 2008). "The MDM2 SNP genotypes were examined to determine if they could be linked to an increased cancer susceptibility, age of cancer diagnosis, pathological variables and clinical outcome." (PMID 18828900, 2008). "MDM2 is a transcription factor that is oncogenic when highly expressed and spontaneously leads to tumorigenesis, and it has been reported to be overexpressed in many human tumors and is associated with infiltration, metastasis, and poor prognosis of many malignant tumors." (PMID 38338471, 2024).
cancer (continued). "Furthermore, targeting overexpressed MDM2 on cancer cell membranes could also cause membrane destabilization and rapid cancer-specific necrosis." (PMID 29584707, 2018). "Also the fact that mice carrying the human MDM2 SNP309G allele only displayed elevated MDM2 expression in a few tissues supports the hypothesis that SNP309 may act as a cancer risk factor in distinct tissues only." (PMID 28158999, 2017). "Taken together, these findings suggests the del 1518 ins/del variant may have different effects on risk for cancer development in different organs, partly dependent on interactions with other MDM2 SNP variants, similar to what has been observed for promoter variants like SNP309 and SNP285." (PMID 28158999, 2017). "Therefore, polymorphisms and mutations affecting MDM2 expression may contribute to the susceptibility to various cancers." (PMID 27890964, 2016). "Thus, the new SNP detection method is considered useful for detecting the SNP c.309T>G in the MDM2 gene so as to judge cancer susceptibility against some cellular stress in the clinical setting, and also to handle a large number of samples and enable rapid clinical diagnosis." (PMID 23565197, 2013). "Evidence suggests that MDM2 T309G polymorphism may be a risk factor for several cancers." (PMID 22844496, 2012). "Thus, it is possible that reduced MDM2 levels expected in TT individuals could lead to elevated ER expression, and hence may elevate cancer risk - a hypothesis that requires further investigation." (PMID 20219101, 2010).